MEF2A (myocyte enhancer factor 2A)
Diseases named in the same sentence as MEF2A in open-access papers (continued):
Sharing a sentence is not in itself a finding about the gene and the disease.
asthma (1 paper, 2012). "We identified two novel variants in two genes, DST and MEF2A, that had high coverage and could potentially be risk, MEF2A, or protective, DST, asthma variants." (PMID 23046476, 2012).
atopic dermatitis (1 paper, 2023). "Mechanistically, exosomal microRNA-147a repressed pathological angiogenesis and inflammatory injury during atopic dermatitis progression by targeting VEGFA and MEF2A-TSLP axis." (PMID 37264030, 2023). "microRNA-147a-overexpressing adipose-derived stem cells-derived exosomes suppressed pathological angiogenesis and inflammatory injury in atopic dermatitis by targeting VEGFA and MEF2A-TSLP axis." (PMID 37264030, 2023).
atrial fibrillation (1 paper, 2017). A disorder characterized by an electrocardiographic finding of a supraventricular arrhythmia characterized by the replacement of consistent P waves by rapid oscillations or fibrillatory waves that vary in size, shape and timing and are accompanied by an irregular ventricular response. "As a whole, our data imply that regulatory polymorphisms which alter expression levels of upstream regulators of this gene network (such as Nkx2-5, Mef2a, SRF, Nostrin, Znf451, and Ttn) might predispose to atrial fibrillation." (PMID 28720711, 2017).
bladder cancer (1 paper, 2021). "Using the T24 human bladder cancer cell line, we confirmed that silencing of SEC23A expression inhibited the MAPK signaling pathway and MEF2A expression." (PMID 34456965, 2021). "Next, we found MEF2A gene expression in advanced tumor samples was significantly higher than that in early stage tumor samples, consistent with the oncogenic role of SEC23A in bladder cancer." (PMID 34456965, 2021).
bladder tumor (1 paper, 2025). "Besides, upregulated MEF2A increases lncRNA SNHG16 expression, contributing to gemcitabine resistance in the starving bladder tumor microenvironment." (PMID 40592832, 2025).
breast tumors (1 paper, 2020). "To explore the clinical significance of the MITR (HDAC9)/MEF2A/IL11 axis in TNBCs, we performed immunohistochemical (IHC) analyses on 44 primary breast tumors and 4 noncancerous mammary controls with the MITR antibody." (PMID 33042272, 2020).
cardiac arrhythmia (1 paper, 2023). Any disturbances of the normal rhythmic beating of the heart or MYOCARDIAL CONTRACTION. "Given that Mef2a knockout mice die suddenly with terminal cardiac arrhythmias, we assessed Mef2a localization within the VCS and observed expression in the AVB and right bundle branch (RBB)." (PMID 36454649, 2023).
Cirrhosis (1 paper, 2019). A chronic disorder of the liver in which liver tissue becomes scarred and is partially replaced by regenerative nodules and fibrotic tissue resulting in loss of liver function. "Our data showed that the levels of MEF2A, C, and D proteins were high in liver tissues from patients with cirrhosis and increased during culture-induced activation of primary H-HSCs." (PMID 31031620, 2019).
cognitive decline (1 paper, 2025). "Also, MEF2A has been identified as a negative regulator in AMPA receptor expression, which participates in memory processes, suggesting that this transcription factor could be involved in cognitive decline in SZ." (PMID 40332239, 2025).
Crohn disease (1 paper, 2014). A gastrointestinal disorder characterized by chronic inflammation involving all layers of the intestinal wall, noncaseating granulomas affecting the intestinal wall and regional lymph nodes, and transmural fibrosis. "Using our network analysis, we identified MEF2A as the factor with the highest association with Crohn's disease." (PMID 24516403, 2014). "We validate the association of one of our novel TF-disease associations, MEF2A and Crohn's disease, suggesting that our approach generates testable disease association hypotheses." (PMID 24516403, 2014). "Finally, we validate one such association between MEF2A and Crohn's disease." (PMID 24516403, 2014). "We found that expression of MEF2A itself was significantly higher in Crohn's disease patients (P = 0.0013, Wilcoxon rank-sum test)." (PMID 24516403, 2014). "As an example, we found a link between MEF2A and Crohn's disease, which we validated in an independent expression dataset." (PMID 24516403, 2014). "Additionally, among genes targeted by MEF2A, genes in module 262 also exhibited a higher level of differential expression among patients with Crohn's disease (P = 0.0019)." (PMID 24516403, 2014). "In addition, our factor-disease network suggests a novel role for MEF2A in Crohn's disease – an association that would not have been found using the naive method (naive adj." (PMID 24516403, 2014).
developmental delay (1 paper, 2008). "The MEF2-family is an ancient mediator of signal-dependant transcription and diverse developmental programs and MEF2A was quite recently demonstrated to be involved in morphogenesis of postsynaptic neurons which implicate that it could also contribute to the developmental delay seen in the patient." (PMID 18194513, 2008).
diffuse midline glioma (1 paper, 2024). A diffuse glioma that arises from the midline structures of the central nervous system. "A recent study demonstrated that in diffuse midline glioma, ERK5 regulates the proglycolytic isoenzyme 6-phosphofructo-2-kinase/fructose-2,6-biphosphatase 3 (PFKFB3) via the activation of transcriptional factor MEF2A." (PMID 38542254, 2024).
dilated cardiomyopathy (1 paper, 2022). Cardiomyopathy which is characterized by dilation and contractile dysfunction of the left and right ventricles. "Rbfox1 also regulates splicing of a MEF2A exon in mouse and zebrafish heart that is mis-spliced in cells from human patients with dilated cardiomyopathy, and Rbfox1 and Rbfox2 cooperatively regulate splicing of Mef2D during C2C12 differentiation." (PMID 34996845, 2022).
Duchenne muscular dystrophy (1 paper, 2025). Duchenne muscular dystrophy (DMD) is a neuromuscular disease characterized by rapidly progressive muscle weakness and wasting due to degeneration of skeletal, smooth and cardiac muscle. "It has been shown before by qPCR that many “DM1-specific” splice events are shared between DM1 and Duchenne muscular dystrophy (DMD) including, among others, MBNL1, ATP2A1, TTN, TNNT2 and MEF2A/C." (PMID 40149583, 2025).
embryonal carcinoma (1 paper, 2016). A non-seminomatous malignant germ cell tumor characterized by the presence of large germ cells with abundant cytoplasm resembling epithelial cells, geographic necrosis, high mitotic activity, and pseudoglandular and pseudopapillary structures formation. "Indeed, Mef2a expression has been shown to be regulated by BMP-2 upon differentiation of the cardiomyocyte-like CL6 cell line, a subclone derived from P19 embryonal carcinoma cells." (PMID 27630998, 2016).
glioblastoma (1 paper, 2013). The most malignant astrocytic tumor (WHO grade IV). "Comment: The manuscript contains interesting observations regarding miR-379/miR-656 locus in glioblastoma and its likely regulation by MEF2A." (PMID 23618224, 2013). "MEF2A was measured in several glioblastomas and found to be reduced relative to controls, consistent with previous reports that MEF2 regulates expression of the locus." (PMID 23618224, 2013).
inflammatory bowel disease (1 paper, 2014). A spectrum of small and large bowel inflammatory diseases of unknown etiology. "MEF2A has been previously associated with cardiovascular disease, but is not recognized to have a role in inflammatory bowel disease." (PMID 24516403, 2014).
neuroblastoma (1 paper, 2019). Neuroblastoma (NB) is the most common solid, extracranial childhood tumor. "The expression of SENP2 markedly increased the activity of MEF-2A in neuroblastoma cell lines and it mediated the activity dependent regulation of MEF-2A based on the stimuli, thus playing an important role in the activation dynamics of MEF-2A." (PMID 31105874, 2019).
preeclampsia (1 paper, 2025). Preeclampsia is a hypertensive disorder of pregnancy that is characterized by new-onset hypertension with proteinuria presenting after 20 weeks of gestation, and depending on mild or severe forms may initially present with severe headache, visual disturbances, and hyperreflexia. "MEF2A expression was concomitant with p38 MAPK and ERK5 activation, both of which control a multitude of functions disrupted in preeclampsia, including cell division, differentiation, survival, angiogenesis, and immune responses." (PMID 41416997, 2025).
pregnancy disorder (1 paper, 2023). A disorder that is related to pregnancy. "MEF2A is expressed much higher than other three MEF2 members in primary human cytotrophoblasts, and induces cytotrophoblast differentiation and syncytium formation, suggesting dysregulation of MEF2A may be associated with placenta-related pregnancy disorders." (PMID 37008050, 2023).
prostate carcinoma (1 paper, 2021). A carcinoma that arises from epithelial cells of the prostate gland. "Implications of MEF2A in human cancer were discovered in prostate cancer, and MEF2A was shown to participate in stress-induced progression of prostate cancer as a p38 substrate." (PMID 33863999, 2021).
psoriasis (1 paper, 2013). An autoimmune condition characterized by red, well-delineated plaques with silvery scales that are usually on the extensor surfaces and scalp. "Many DEG-coded proteins (CCNA2, FYN, PIK3R1, CTGF, F3) and transcription factors (AR, TFDP1, MEF2A, MECOM) were identified as central nodes, suggesting their potential role in psoriasis pathogenesis." (PMID 24303025, 2013).
rhabdomyosarcoma (1 paper, 2015). A rare aggressive malignant mesenchymal neoplasm arising from skeletal muscle. "Interestingly, in rhabdomyosarcoma samples, MEF2A level positively correlated with myogenin expression, whereas myogenin level also positively correlated with myosin heavy chain 2 (MYH2A), a marker of late differentiation." (PMID 26384300, 2015).
soft tissue sarcoma (1 paper, 2025). A malignant neoplasm arising from muscle tissue, adipose tissue, blood vessels, fibrous tissue, or other supportive tissues excluding the bones. "TCGA dataset in soft tissue sarcoma showed that PGAM2 expression positively correlates with MEF2A and MEF2D expression." (PMID 40707487, 2025).
T-cell leukemia (1 paper, 2015). A malignant disease of the T-lymphocytes in the bone marrow, thymus, and/or blood. "A heightened MEF-2A expression in ATL patients could suggest a direct role of MEF-2A in the genesis and/or maintenance of T-cell leukemia in these patients." (PMID 25809782, 2015).
teratoma (1 paper, 2020). A non-seminomatous germ cell tumor characterized by the presence of various tissues which correspond to the different germinal layers (endoderm, mesoderm, and ectoderm). "The level of mRNAs encoding Pax3 was significantly higher, while the expression of Nfix, Eno3, Mck, Mef2a, and Itga7 was significantly lower in Pax7−/− teratomas, as compared to Pax7+/+ ones." (PMID 32552916, 2020). "The level of mRNAs encoding Pax3 was significantly higher, while the expression of Nfix, Eno3, Mck, Mef2a, and Itga7 was significantly lower in Pax7−/− teratomas, as compared to Pax7+/+ teratomas." (PMID 32552916, 2020).
ventricular septal defect (1 paper, 2025). The presence of a defect (opening) in the septum that separates the two ventricles of the heart. "Mettl3 deficiency-induced downregulation of MEF2A, SOX4, and SOX11 expression could lead to congenital cardiac defects, including left pulmonary stenosis, ventricular septal defects, and right ventricular hypoplasia." (PMID 40303284, 2025).
tumor (24 papers, 2006 to 2025). "The immunohistochemistry (IHC) results indicated that E_349, when deleted or extensively mutated, showed a relatively low expression of MEF2A and a markedly stronger ability for tumor proliferation." (PMID 37904237, 2023). "Univariate Cox proportional hazard analysis showed that high levels of MEF2A, poor differentiation of the tumor tissues, and tumor grade were significantly associated with unfavorable prognostic risk." (PMID 33863999, 2021). "MAZ is an oncogenic transcription factor associated with multiple cancers; while MEF2A is tumor repressive and its mutation is associated with tumorigenesis." (PMID 32483180, 2020). "Since the expression level of MEF2A is associated with patient prognosis, we speculated whether inhibition of E_349 could affect tumor survival phenotypes and drug sensitivity (e.g., vemurafenib)." (PMID 37904237, 2023). "Indeed, dysfunction of MEF2A has been associated with cardiovascular disease, neurodegenerative disease and tumor progression." (PMID 37008050, 2023). "The results demonstrated that cetuximab inhibited tumor growth in nude mice, as indicated by the decreases in tumor size and weight, meanwhile, silencing of MEF2A enhanced the efficacy of cetuximab." (PMID 40592832, 2025). "As a phosphatase, PP1α has many nuclear substrates such as phosphorylated mouse double minute 2, myocyte enhancer factor 2A, retinoblastoma (p‐Rb), and cAMP‐response element binding protein, playing a pivotal role in tumor progression." (PMID 39036343, 2024). "Then, we found that MEF2A is significantly downregulated in TCGA-SKCM tumor samples (tumor cell: 461 and normal cell: 558, adjusted p-value = 5.59e − 68, ANOVA test)." (PMID 37904237, 2023). "Through a series of basic experiments, we observed that MEF2A expression is higher in normal kidney tissue than in RCC tumour tissue." (PMID 37859585, 2023). "In xenograft mice, MEF2A overexpression in RCC cells led to reduced tumour size compared to the control group." (PMID 37859585, 2023). "In the xenograft assay, the Lv‐MEF2A group exhibited reduced tumour size, weight and volume compared to the vector group, indicating that MEF2A can inhibit tumour growth in RCC." (PMID 37859585, 2023). "Clearly, additional research is required to allow more accurate conclusions about the role of MEF2A in tumor development and progression." (PMID 37008050, 2023). "In agreement with the results of qPCR, the levels of the MEF2A protein were elevated in tumor tissue samples compared to that in the control samples." (PMID 33863999, 2021). "The results demonstrated that silencing MEF2A decreased the frequency of tumor formation and tumor growth rate, and overexpression of MEF2A achieved the opposite effects." (PMID 33863999, 2021). "The results showed that only the expression of MEF2A mRNA was consistently higher in the tumor tissues than that in adjacent tissues, and statistical analysis indicated significant differences." (PMID 33863999, 2021). "The results of the staining indicated that 59.01% of the tumor tissue samples and 10.56% of adjacent tissue samples showed positive staining for MEF2A, and the staining intensity was stronger in the tumor tissues than that in adjacent tissues." (PMID 33863999, 2021). "Effects of MEF2A on tumor cell colonization and dissemination were assessed in two metastasis models." (PMID 33863999, 2021). "Mechanistically, SOX2 upregulation is attributed to the binding of the acetylated myocyte enhancer factor 2A (MEF2A) to SOX2 promoter in tumor cells." (PMID 31887658, 2020). "As we all know, MEF2A is a transcription factor that may influence tumor progression by regulating gene expression." (PMID 40066751, 2025). "A past study showed that miRNA could enhance the mitochondrial function and activate OXPHOS by downregulating MEF2A, while tumor-related genes enhance OXPHOS through metabolic reprogramming to inhibit sensitivity to TKI drugs." (PMID 37394466, 2023).
tumor (continued). "So, we deemed that MEF2A expression is lower in RCC tumour tissues." (PMID 37859585, 2023). "MEF2A could promote the proliferation and metastasis of tumor cells by inducing epithelial-mesenchymal transition (EMT) and activating the WNT/β-catenin signaling pathway." (PMID 34957213, 2021). "However, some genetic mutations, such as those in HLA-B, MEF2A, RHOA, and NAV3, were associated with a high tumor proliferation index in this study." (PMID 33747936, 2021). "A subcutaneous xenograft model was used to explore the effects of MEF2A on tumor growth." (PMID 33863999, 2021). "Overall, these results demonstrated that MEF2A may play an important role in the acceleration of tumor progression." (PMID 33863999, 2021). "Thus, the tumor volume and weight in animals of the high MEF2A expression group were considerably higher than those in the low MEF2A expression group." (PMID 33863999, 2021). "Moreover, the staining intensity of MEF2A was considerably stronger in poorly differentiated and late-stage tumor tissues than that in well-differentiated and early-stage tumor tissues." (PMID 33863999, 2021). "Although the pathway plays an important role in PA, defects in MEF2A have never been associated to this tumour." (PMID 24860619, 2014). "However, other studies have reported tumor suppressive activity for MEF2A." (PMID 37008050, 2023). "The most significant CRISPRi screened enhancer E_349 interacts with MEF2A and LRRC28 instead of its designed target IGF1R, which implies that HRR-associated enhancers could modulate multiple uncharacterized melanoma cancer genes for tumor survival." (PMID 37904237, 2023). "In vivo and in vitro functional assays revealed that silencing MEF2A substantially enhanced cetuximab sensitivity to CRC cells, thus promoting the anti-tumor effect of cetuximab on CRC." (PMID 40592832, 2025). "MEF2A transcriptionally upregulates the expression levels of catenin beta 1 (CTNNB1) and zinc finger E-box binding homeobox 2 (ZEB2) in CRC to promote tumor progression." (PMID 40592832, 2025). "More generally, our study raises the possibility that targeting MEF2A-dependent inflammatory gene expression by cAMP-eliciting environmental cues may be a general mechanism linking tissue homeostasis and immune control, which may become aberrant during tumor progression or microbial infection." (PMID 34129840, 2021). "All proteins were expressed in tumor cells, and expression was also seen in stroma cells for HK2, MEF2A, and MSN." (PMID 17054779, 2006). "The structure of the MEF2A gene is highly homologous to that of the MEF2C gene, and MEF2A plays a key role in embryonic development similar to MEF2C; however, MEF2A is poorly characterized and has been rarely studied in the context of tumor progression." (PMID 33863999, 2021). "Additionally, our GSEA analysis revealed that MEF2A might inhibit RCC progression by the Wnt signalling pathway, which is crucial in tumour progression and influences the tumour microenvironment." (PMID 37859585, 2023). "However, under certain pathological conditions, MEF2A may also have detrimental functions by promoting SMC aging, myocardial hypertrophy and fibrosis, and tumor progression." (PMID 37008050, 2023). "Although MEF2A and MEF2D have been linked to differentiation of muscle and cardiac cells, in the absence of regular growth signals, tumor cells may proliferate due to dysregulation of the MEF2 family, which can cause unchecked growth and aberrant metabolic adaption." (PMID 41155227, 2025). "For example, MEF2A may play a dual role in promoting tumor proliferation and metastasis by inducing the activation of EMT and WNT/beta -catenin signaling, whereas TCF7L2 serves as a core TF of the WNT signaling pathway, and is involved in regulating tumor cell proliferation and migration." (PMID 39712016, 2024).